GAS6 (growth arrest specific 6)
Diseases named in the same sentence as GAS6 in open-access papers (continued):
Sharing a sentence is not in itself a finding about the gene and the disease.
tumor (continued). "In B16/F10 melanoma, GAS6 expression increased with tumor growth in vivo while Protein S was expressed at a high level from the onset." (PMID 39062902, 2024). "Their findings revealed a positive correlation between AXL expression, TGF-β, and its receptor in disseminated prostate cancer cells, indicating a crucial crosstalk between TGF-β and the Gas6/Axl signaling pathways that regulate tumor dormancy." (PMID 38795254, 2024). "By binding to its receptors (Axl, Mertk, Tyro3), Gas6 is known to significantly affect cell cycle progression in cancer cells, promote angiogenesis, and modulate the immune environment of the tumor." (PMID 39255000, 2024). "We observed altered molecular crosstalk with tumor cells, e.g., through activation of Gas6 signaling across several cell types." (PMID 38566128, 2024). "Previous studies have shown that Gas6 is able to regulate tumor cell migration and invasion through the JAK2/ERK, SRC, and Akt/GSK-3β/β-catenin pathways." (PMID 39451556, 2024). "The overexpression of AXL, a TAM receptor, together with growth arrest-specific 6 (GAS6), an antiapoptosis and pro-cell growth ligand, promotes tumor cell invasion in various malignancies, including HCC." (PMID 39590305, 2024). "Mechanistically, growth arrest-specific 6 (Gas6) expressed by neutrophils activates AXL receptors on tumor cells, promoting their regeneration." (PMID 38760815, 2024). "Gas6-containing EVs derived from tumor perivascular cells induce endothelial progenitor cells (EPCs) recruitment by stimulating Gas6/Axl pathway to promote the rebound effect of CRC vascularization after the AA-TKI cessation." (PMID 38741166, 2024). "GAS6 is a vitamin-K-dependent growth factor expressed by several cells like monocytes, endothelial cells, brain, heart, fibroblast, and tumor cells and has the best affinity for AXL among all the TAM family members." (PMID 38391974, 2024). "In the tumor microenvironment, GAS6 has been shown to have tumor promoting affects by promoting cell proliferation, inhibiting apoptosis, and dampening NK cells anti-tumor effects." (PMID 38033034, 2023). "In the same study, it was also shown that incubation of human osteosarcoma cell lines with GAS6 protected tumor cells from entering apoptosis and promoted cell migration and invasion." (PMID 38203403, 2023). "Li and collaborators observed that Gas6 interaction with AXL induced tumor cell migration mostly by upregulating Slug in prostate and skin cancer cells." (PMID 37265798, 2023). "Double staining of AXL and OCT4 revealed that OCT4-positive stem cells are significantly reduced in GAS6-CAR-T group, thereby indicating that GAS6-CAR-T can target CSCs in vivo to enhance tumor clearance in consistent with the in vitro effects on CSCs." (PMID 37475048, 2023). "It is thought that be Gas6/Axl signaling pathway mediates the crosstalk between tumor and immune cells, thereby contributing to immune suppression and evasion within the tumor microenvironment to facilitate the growth of tumors, survival, and metastasis." (PMID 38370978, 2023). "Gas6 signaling inhibition appears to confer dual benefits: potentially reversing the epithelial-to-mesenchymal transition (EMT) of tumor cells and promoting NK cell activation." (PMID 37760801, 2023). "The administration of anti-Gas6 neutralising antibodies also promotes NK cell activation and suppresses metastatic tumour development in a mouse pancreatic cancer model." (PMID 37313600, 2023). "The increased expression of AXL and GAS6 proteins was correlated with less differentiated histological grading, tumor stage and lymph nodes involvement." (PMID 37469409, 2023). "To test the effects of GAS6-CAR-T cells on tumor growth in vivo, we established a xenograft mouse model by injecting PANC1 cells subcutaneously." (PMID 37475048, 2023).
tumor (continued). "Further, by constructing a gene regulatory network for LUSC, we found that there is a common ligand signal GAS6 in tumor progression, but the target genes regulated by GAS6 are obviously different." (PMID 37189418, 2023). "The GAS6/AXL signalling pathway has been shown to promote tumour cell proliferation and survival as well as EMT and immune evasion." (PMID 37313656, 2023). "Research has shown that Gas6 is expressed in host stromal cells, including fibroblasts, macrophages, and DCs within the tumor microenvironment." (PMID 38370978, 2023). "The growth arrest-specific protein 6 (GAS6)/AXL axis is upregulated in various tumor tissues, and it has been suggested to be another antiapoptotic pathway in addition to the BCL-2 family in some tumors." (PMID 36313732, 2022). "Gas6 expression was decreased in tumor tissues in BLCA, LUSC, and LUAD, predicting better OS in BLCA and LUSC but worse OS in LUAD." (PMID 36059952, 2022). "We assessed the protein expression level of the TAM receptor Axl and its ligand Gas6 in primary HNSCC tumor samples derived from a single center retrospective cohort of patients treated for HNSCC with curative intent in a tissue microarray format." (PMID 35406601, 2022). "In contrast to the dormancy-inducing effect of LIF, CXCL12 and Gas6, the inflammatory cytokine IL-1β promoted tumour proliferation and subsequently triggered overt metastasis of breast tumour cells." (PMID 36307871, 2022). "As a result, the TAM signaling pathway mediated by GAS6-AXL regulates the tumour microenvironment and biological behaviour of this cell line." (PMID 36203174, 2022). "With all chemotherapeutic treatments, metastatic tumour burden temporarily decreased but was followed by metastatic relapse which was accompanied by an influx of Gas6-expressing neutrophils into metastatic lesions." (PMID 35022267, 2022). "Specifically, we found that chemotherapy induces the expression of neutrophil chemoattractants in tumour cells and subsequent recruitment and infiltration of Gas6 expressing neutrophils to the liver in a CXCR2-dependent manner." (PMID 35022267, 2022). "These neutrophils express growth arrest specific 6 (Gas6) which leads to AXL receptor activation on tumour cells enabling their regrowth." (PMID 35022267, 2022). "It was reported that Gas6 expression was associated with tumor progression and patient survival in RCC, and low tumor Axl mRNA levels were independently correlated with improved survival." (PMID 36059952, 2022). "The Gas6 (natural ligand) /Axl signaling promotes tumor cell survival, proliferation, migration, invasion, angiogenesis, therapeutic resistance, and immune evasion." (PMID 36551940, 2022). "Evidence has proven that Gas6 produced by osteoblasts can also induce tumour dormancy during bone metastasis." (PMID 36307871, 2022). "Upon binding to AXL, GAS6 activates downstream signaling pathways and promotes tumor cell survival, proliferation, migration, and other activities." (PMID 36313732, 2022). "TAM receptors and their ligands PROS1 and GAS6 are frequently overexpressed in cancer and mediate tumor-stroma interaction to limit anti-tumor immunity and fuel cancer growth." (PMID 36509738, 2022). "Warfarin has been shown to block the g-carboxylation growth arrest-specific 6 (GAS6) protein, which decreases tumor cell migration and proliferation." (PMID 35613184, 2022). "We found that Gas6 expression was decreased in tumor tissues in BLCA, LUSC, and LUAD, predicting a better OS in BLCA and LUSC but worse OS in LUAD, which indicated that the specific role of Gas6 in certain cancers needs to be further investigated." (PMID 36059952, 2022). "Collectively, all above data indicated that tumour intrinsic PD-L1 promotes cell proliferation via Gas6/MerTK signaling in vitro and in vivo." (PMID 33139930, 2021). "Several studies have revealed that GAS6/AXL signaling plays a vital role in promoting the immune-suppressive tumor microenvironment." (PMID 34778071, 2021).
tumor (continued). "Several engineered AXL decoy receptors with 80-fold higher affinity for GAS6 compared to the wild-type AXL receptor significantly reduced tumor burden and metastasis in vivo." (PMID 34830794, 2021). "Stromal cell-derived GAS6 was also shown to promote tumor cell migration, invasion, survival, and proliferation." (PMID 34778071, 2021). "Still, preclinical and clinical findings for various Gas6 and Axl inhibitors are favorable and make targeting this axis an attractive and promising approach to impair tumor progression and dissemination." (PMID 34576116, 2021). "In FAK-depleted pericytes, activated Pyk2 increases Gas6 transcript levels and signals via the Gas6/Axl/Akt/Cyr61 pathway to promote tumor cell proliferation and angiogenesis." (PMID 34576116, 2021). "The binding of Gas6 to AXL induces pathways involved in tumor cell growth, invasion, EMT, angiogenesis, drug resistance, immune regulation, and CSC maintenance." (PMID 33805447, 2021). "Tumour secretion of IL-10 promotes the upregulation and secretion of growth arrest specific 6 (GAS6; the ligand for AXL) in macrophages which, in turn, enhances cancer cell AXL signalling within the TME." (PMID 34944851, 2021). "AXL is a member of the TAM family, and it transduces signal through the high-affinity ligand growth arrest-specific protein 6 (GAS6), thereby driving the proliferation, migration and invasion of tumour cells." (PMID 34335945, 2021). "TPC‐EV‐derived Gas6 promotes EPC recruitment into tumours for revascularization by activating the Axl pathway." (PMID 34035882, 2021). "In our current study, we have shown that tumour PD-L1 activated intra-tumour cell Gas6/MerTK signals which promoted NSCLC cell proliferation in vitro and in vivo." (PMID 33139930, 2021). "GAS6 is produced by CAFs and other cells within tumour tissue, and externalized PtdSer is abundant due to stress- and cell death-causing conditions, such as oxygen radicals or hypoxia." (PMID 34638349, 2021). "It was demonstrated that osteoblast-derived GAS6 induces AXL expression in tumor cells, which suggests that paracrine GAS6/AXL signaling promotes survival, inhibits apoptosis, and mediates homing of tumor cells to the bone." (PMID 34778071, 2021). "Axl expression in prostate cancer cell lines has been shown to be required for regulation of TGF-β signaling and for TGF-β2-mediated induction of tumor cell dormancy induced by osteoblasts following release of Gas6." (PMID 33805598, 2021). "It is possible that in tumour microenvironment, where the level of GAS6 is high, AXL takes a central stage." (PMID 34638349, 2021). "Zweemer and colleagues demonstrated that warfarin disrupts the phosphatidyl serine (PS)–Gas6 interaction and consequently impairs tumor cell migration." (PMID 34576116, 2021). "Gas6 silence and an Axl inhibitor markedly inhibit tumour revascularization by impairing EPC recruitment." (PMID 34035882, 2021). "Especially in macrophages, in vitro studies suggested that tumor cells or tumor cell-conditioned media induce GAS6 expression and secretion." (PMID 34778071, 2021). "It is therefore possible that Gas6 is involved in the homing of tumor cells to the bone microenvironment." (PMID 33791875, 2021). "The results showed that treatment with AVB-500 decreases Gas6-induced Axl and Src phosphorylation, tumor vessel density, tumor growth, and metastatic burden." (PMID 34576116, 2021). "Collectively, these data suggest that TPC‐EV‐derived Gas6 is involved in promoting EPC recruitment for tumour revascularization by after AA‐TKI therapy." (PMID 34035882, 2021). "As such, the Gas6/Axl pathway has gained attention as a promising therapeutic target for drug development in multiple tumor types." (PMID 34576116, 2021). "Mechanistically, tumour perivascular cell‐derived extracellular vehicles (TPC‐EVs) contain Gas6 that instigates the recruitment of endothelial progenitor cells (EPCs) for tumour revascularization via activating the Axl pathway." (PMID 34035882, 2021).
tumor (continued). "While the function of Gas6-Axl signaling on tumor cell proliferation, EMT, migration and drug resistance has been extensively studied, only a few studies have investigated the role of Gas6/Axl signaling in the immune system in the context of cancer." (PMID 32174917, 2020). "Over the past decade, research has focused on elucidating the functional role of Gas6/Axl signaling in tumor progression." (PMID 32483414, 2020). "Using immunohistochemistry and immunofluorescence, expression of Gas6 and Axl, which promote tumor cell migration and invasion, was examined in carcinoma tissues and adjacent normal tissues from EC patients." (PMID 32432570, 2020). "AXL, the high-affinity ligand growth arrest-specific protein 6 (GAS6), is involved in multiple tumor processes, including proliferation, angiogenesis, invasion, metastatization, immune regulation, stem cell maintenance, EMT, and drug resistance." (PMID 33072597, 2020). "Reciprocally, we found that hMENA/hMENAΔv6 regulate the AXL ligand GAS6 expression and secretion in CAFs, indicating hMENA as a crucial player in the tumor invasiveness mediated by the cooperativity between cancer cells and CAFs." (PMID 32909687, 2020). "Most of the AXL signaling is triggered by its ligand, growth arrest-specific gene 6 (GAS6); however, hypoxic conditions in the tumor microenvironment also play a critical role in the activation of GAS6-AXL signaling." (PMID 33374832, 2020). "This review focuses on the role of the Gas6/Axl signaling pathway in promoting the immunosuppressive tumor microenvironment, as immune evasion is considered one of the hallmarks of cancer." (PMID 32660000, 2020). "Here we identify pericyte FAK as a negative regulator of tumour angiogenesis and tumour growth, through its control of Gas6-stimulated Axl activation." (PMID 32499572, 2020). "The number of NK cells, and in particular the number of proliferating NK cells, was also increased in tumor draining lymph nodes from anti-Gas6 treated mice compared to control treated mice." (PMID 32174917, 2020). "This subpopulation differentially expresses genes that have been shown to be tissue-reparative (Hmox1, Gas6) and tumor-promoting (Pf4, Fgfr1, and Nrp2)." (PMID 33072601, 2020). "INCB081776 treatment also increased total MERTK levels in both tumor models, as well as GAS6 levels in CTG-2041." (PMID 33425754, 2020). "Gomes and colleagues showed that stromal cell-derived Gas6 promotes tumor cell migration, invasion, survival, and proliferation." (PMID 32660000, 2020). "Leukocyte-derived Gas6 was shown to mediate tumor growth in a syngeneic TNBC mouse model (4T1) as well as in other cancer cell models." (PMID 32352034, 2020). "To this end, we treated PANC‐1 for 48 h with CM derived from P‐CAFs silenced for GAS6 expression, and we observed that GAS6 silencing in CAFs reduced tumor cell invasion, as hMENA/hMENAΔv6 silencing in CAFs did." (PMID 32909687, 2020). "This review focuses on the role of Gas6/Axl signaling in the tumor microenvironment, and its relation to potential mechanisms of immune evasion." (PMID 32660000, 2020). "The Gas6/Axl signaling pathway influences cancer development and progression through its effect on tumor cell proliferation, invasion, metastasis, epithelial-mesenchymal transition (EMT), and angiogenesis." (PMID 32370748, 2020). "The Gas6/Axl signaling pathway in neoplastic cells mediates multiple aspects of tumor progression and metastasis, including tumor cell proliferation, migration, invasion, survival, angiogenesis, therapeutic resistance, and immune evasion." (PMID 32660000, 2020). "Overall our study identifies that pericyte FAK expression protects against enhanced tumour growth via the regulation of pericyte Gas6-Axl-AKT-signalling pathway and subsequent control of Cyr61." (PMID 32499572, 2020).
tumor (continued). "Strong expression of Axl and Gas6 was observed in the tumor margins and in the vascular invasion while 8/10 cases (80%) with lymph node metastases had positive Axl in the primary tumor." (PMID 32092888, 2020). "Stimulation of Axl by the ligand Gas6 enhances tumor cell invasion and migration, and Gas6/Axl complexes enhance the expression of transcription factors that promote epithelial-mesenchymal transition (EMT)." (PMID 32432570, 2020). "The ability of gal-8 to promote expression of Gas6, and the observed reduced expression of Gas6 in gal-KO mice, points at gal-8 as a potential physiological inducer of Gas6 expression that supports tumor progression." (PMID 32355198, 2020). "Khoo and colleagues demonstrated that osteoblast-derived Gas6 induced Axl expression on neoplastic cells, suggesting that paracrine Gas6/Axl signaling promotes survival, inhibits apoptosis, and mediates homing of tumor cells to the bone." (PMID 32660000, 2020). "In GAS6–/– knockout mice, early stage progression and time to tumor formation are decreased, but established tumor growth is unaffected." (PMID 32148495, 2020). "Differently, we found that PANC‐1 cells express low level of GAS6, in agreement with previous data indicating the role of GAS6 as stromal‐derived factor involved in pro‐tumor paracrine‐mediated communication." (PMID 32909687, 2020). "Here, the authors show that deletion of pericyte FAK upregulates Gas6-Axl mediated Cyr61 production, which increases endothelial cell proliferation and angiogenesis, while elevating tissue factor production to enhance tumour cell proliferation." (PMID 32499572, 2020). "The third promoter of tumor growth whose expression is induced by gal-8 is Gas6, the ligand of the TAM family (Tyro3, Axl, and Mer) of receptor tyrosine kinases." (PMID 32355198, 2020). "Together, these studies implicate Gas6/Axl signaling as an important pathway driving tumor growth and metastasis." (PMID 32483414, 2020). "At the same time, hMENAΔv6 promotes tumor receptor overexpression, supporting the GAS6/AXL axis involvement in tumor progression." (PMID 33182542, 2020). "GAS6 is a crucial factor involved in paracrine stroma‐tumor cell interaction, as evidenced by several studies, and the GAS6‐AXL axis has been implicated in the reciprocal signaling between PDAC and stromal cells induced by KRASG12D mutation." (PMID 32909687, 2020). "Several cancer studies have focused on the role of Gas6-Axl signaling on the tumor cells and have demonstrated that Axl activation supports tumor cell proliferation, epithelial-mesenchymal transition (EMT), drug resistance, migration and metastasis." (PMID 32174917, 2020). "In this model, transplanting bone marrow derived from Gas6−/− mice into WT mice resulted in the slowing of tumor growth, suggesting that Gas6 from BMDCs supports tumor growth." (PMID 32660000, 2020). "Reciprocally, hMENA/hMENAΔv6 regulates AXL expression in tumor cells, thus sustaining GAS6‐AXL axis, reported as crucial in EMT, immune evasion, and drug resistance." (PMID 32909687, 2020). "summarized that GAS6 promotes tumor progression in various tumors and systems (except intestinal tumor), including the circulatory system, locomotor system, gastrointestinal system, nervous system, and urinary system." (PMID 32346605, 2020). "In the osteoblastic niche, tumor cells require the expression of the Axl receptor to activate it in response to microenvironmental growth-arrest specific 6 (GAS6) to maintain the dormancy state." (PMID 32028565, 2020). "This primes FAKKO pericytes to be more responsive to exogenous Gas6, derived from tumour cells, driving sustained activation of pericyte AKT and enhanced Cyr61 expression." (PMID 32499572, 2020). "CCRC patients with lower levels of tumor Axl receptor expression and higher levels of tumor Gas6 showed significantly increased survival rate." (PMID 30934817, 2019).